IL10 (interleukin 10)
Diseases named in the same sentence as IL10 in open-access papers (continued):
Sharing a sentence is not in itself a finding about the gene and the disease.
tumor (continued). "This seems not be the case in our system, since we found no IL-10 secretion in neutrophil/tumor cells cultures." (PMID 28827632, 2017). "Within the tumor microenvironment, TAMs are forced forwards M2 phenotypes by GBM cells via secreting a wide variety of factors such as IL10, IL4, IL6, M-CSF, macrophage inhibitory factor (MIF), TGFβ, and prostaglandin E2 (PGE2), and subsequently support tumor growth and invasion." (PMID 29132376, 2017). "In murine xenograft tumor models injected with hepatocarcinoma, melanoma or colorectal carcinoma cells, LXA4 is able to suppress tumor growth by targeting IL-10-producing regulatory B cells (Bregs) via dephosphorylation of signal transducer and activator of transcription 3 and ERK." (PMID 28210259, 2017). "Because tumor cells of AITL are derived from follicular helper T-cell, the IL-10–induced M2 macrophage polarization also might contribute to the outcome of PTCL-NOS with follicular helper T-cell variant." (PMID 29100307, 2017). "The M2 phenotype favours tumour growth and metastatic spread through the promotion of angiogenesis, production of metalloproteinases, and inhibition of cytotoxic T lymphocytes (CTLs) by TGF-β and IL-10." (PMID 28913366, 2017). "In this process, dendritic cells (DCs) maturation can be suppressed by changes in the cytokine balance (increased VEGF, TGFβ, IL-10, IL-6, and COX-2 and reduced IL-4, IL-12, IFN-α, and IFN-γ) within the tumor, which significantly impairs the antigen presenting function of these cells." (PMID 28053982, 2016). "In this regard, it is interesting to note that tumor cells develop mechanisms to escape from immune responses through DC suppression, and that tumor microenvironment from both early and late-staged CRC abrogates LPS-induced IL-12 secretion in these cells while increasing IL-10." (PMID 27494857, 2016). "We found that the medium of macrophages treated with the CM derived from AXL-expressing cells, especially from mesenchymal-like cells, was enriched for tumor-promoting mediators, including CCL18, and IL-10, compared with that from macrophages treated with MCF-7-CM." (PMID 28721387, 2016). "Moreover, immune modulators, including TGF β, IL10 and CRP, released by tumor cells impair lymphocyte action in systemic inflammation." (PMID 27198767, 2016). "IL-10 production was significantly reduced, but never totally suppressed in tumour lysate-pulsed DCs." (PMID 26795765, 2016). "Conversely, TAMs isolated from HCC tumours did not elicit such B-cell activation and IL-10 production." (PMID 27853178, 2016). "No measurable IL-10 was detected from the IL-10−/− tumor tissue in contrast to the WT tumor-bearing mice." (PMID 27075020, 2016). "IT treated LLC tumours showed a reduction in the level of IL-10 which should be a favourable outcome however this did not translate into increased survival." (PMID 27412241, 2016). "The strong immune suppressive effects of IL-10 might indicate a role for CLEC-2 positive myeloid cells in immune suppression and tumor progression." (PMID 27564117, 2016). "Increased serum IL-10 levels could facilitate development of tumors by suppressing the expression of MHC class I and II antigens and preventing tumor antigen presentation to CD8-cytotic T lymphocytes." (PMID 27220278, 2016). "Tumour-infiltrating MDSCs treated with C-dextran and PEI secreted significantly higher levels of IL-12 and TNF-α, but produced lower levels of IL-10 and TGF-β than the control group." (PMID 27074905, 2016). "Nevertheless, few reports indicate that TNF may also have an anti-tumor effect in CAC, possibly by providing early antibacterial protection in Il10−/− mice." (PMID 27148488, 2016). "In hypoxic areas, TAMs stimulate angiogenesis by secreting TGF-β, VEGF, granulocyte macrophage (GM)-CSF, TNF-α, IL-1, IL-6, and IL-8, promote tumor cell migration and invasion via matrix metalloproteinases (MMPs), TNF-α, and IL-1 and induce immunosuppression via TGF-β, PGE2, and IL-10." (PMID 27044404, 2016).
tumor (continued). "Lack of IL-10 in turn can trigger the production of pro-inflammatory cytokines, prevent anti-tumor immunity and promote tumor growth." (PMID 27489033, 2016). "Indeed, cytokines and growth factors such as IL-10,TGF-β, and VEGF areoverexpressed in tumor tissue just as the chemoattractant factorsMIP-3α/CCL20 are." (PMID 27795841, 2016). "TAMs contribute to IL-10 and TGF-β production, to Treg recruitment by the secretion of CCL22, and promote tumor growth and invasion through production of endothelial growth factor, vascular endothelial growth factor (VEGF), and platelet-derived growth factor (PDGF), among others." (PMID 28003994, 2016). "Interestingly, there were significantly increased numbers of CD4+IFN-γ+ Th1 cells in the tumor, spleen and TDLN harvested from the IL-10−/− B16/F10 mice." (PMID 27075020, 2016). "Moreover, IL10 favors the differentiation of CD4+ cells toward Treg and monocytes toward M2-like macrophages, which accumulate in the tumor microenvironment." (PMID 26956044, 2016). "The aberrant STAT3 signaling in tumor cells can suppress the expression of pro-inflammatory danger signals (e.g., IFNγ, TNF, CXCL10), while induces the expression of immunosuppressive factors (e.g., VEGF, IL-10) that inhibit DCs maturation." (PMID 27917371, 2016). "However, in the current study, we identified an activation role of CD95–CD95L axis in tumours and found that blockade of CD95L effectively attenuated TDC-elicited generation of FcγRIIlow/− activated IL-10-producing B cells." (PMID 27853178, 2016). "Tumor-conditioned medium stimulated increased IL-10 production by spleen cells of control mice and vaccinated mice, but not by spleen cells from tumor-bearing, mock-vaccinated mice." (PMID 27598146, 2016). "Whereas stimulation of M2-like macrophages, with LPS and IFN-γ, did not drastically change their low antitumour activity, M2 macrophages, stimulated by IL-10 alone, had no impact on tumour growth." (PMID 27212807, 2016). "More importantly, the activated FcγRIIlow/− B cells from HCC tumours, but not the resting FcγRIIhigh B cells, without external stimulation suppress autologous tumour-specific cytotoxic T-cell immunity via IL-10 signals." (PMID 27853178, 2016). "Dying tumor cells release various factors (e.g., TGF-β, interleukin-10, or sphingosine-1-phosphate) that lead to M2 polarization of macrophages, which express high levels of arginase-1, ultimately resulting in reduced intratumoral NO abundance, thus contributing to tumor progression." (PMID 27034586, 2016). "PD-1 interaction with its ligand, PD-L1, aberrantly expressed on tumor cells, results in T cell inactivation and apoptosis and inhibited activation of tumor antigen-specific T cells by reducing the production of IL-2, IFN-γ, and stimulating IL-10 production." (PMID 27766079, 2016). "By comparison, normal splenic B cells did not produce measurable levels of IL-10, confirming that IL-10 production is confined to the BCL1 tumor cells." (PMID 27959896, 2016). "We speculated HLA-E induced expression of IL-10 and TGF-β by NK cells via these indirect mechanisms in the tumor-NK cell interaction in vivo." (PMID 27322426, 2016). "In the absence of IL-10, Th1 and Th17 immunity are strongly up-regulated in IL-10−/− B16/F10 tumor-bearing mice." (PMID 27075020, 2016). "Moreover, the interferon-γ/IL-10 ratio was lower in cancer patients compared with COPD patients, consistent with a cytokine milieu favouring tumour tolerance." (PMID 27990285, 2016). "Th2-related cytokines IL-10 and TGF-β1 were involved in tumour immune tolerance." (PMID 26064167, 2015). "Oral intake of mushroom beta-glucan in tumor-bearing mice demonstrated an increase in the gene expression of IL-12 and IFN-γ in tumor tissues and a decrease in serum TGF-β concentration and gene expressions of IL-6, IL-10, COX-2, and TGF-β in the tumor microenvironment." (PMID 26167490, 2015).
tumor (continued). "Under hypoxia, which simulates the tumor microenvironment, OX40 triggering induced IL-10 production from Treg cells, which may provide a suitable environment for tumor progression." (PMID 25744203, 2015). "Accordingly, inhibition of COX-2 prior or during PDT with NSAIDs decreased tumor cell survival in a variety of (tumor) cell lines, which coincided with a reduction in levels of PGE2 and the proangiogenic factors MMP9, TNF-α, IL-1β, IL-10, and VEGF." (PMID 26516076, 2015). "Our results do not provide evidence for overexpression of apoptosis-inducing ligands by DC-tumor cell hybrids, nor did we observe an enhanced production of tolerance-inducing cytokine IL-6 or IL-10 by these cells." (PMID 26605345, 2015). "In contrast, none of these tumor-conditioned media affected LPS-stimulated IL-10 production by BMDMs when compared to non-conditioned BMDMs." (PMID 26177198, 2015). "Moreover, myeloid HO-1-induced expressions of VEGF and IL-10 promoted tumor cell extravasation and STAT3 activation, which are crucial for the survival and successful colonization of tumor cells in metastatic sites." (PMID 25885228, 2015). "In our study, we observed a high level of proinflammatory cytokines, such as TNF-α, IFN-γ and IL-12 in sera from SZU-101-treated tumour-bearing mice, while no induction of TH-2 cytokines IL-4, IL-5 or IL-10 was detected." (PMID 25887995, 2015). "TAMs could mediate EMT of tumor cells and promote the tumor progression through the TLR4/IL-10 signaling pathway." (PMID 26161392, 2015). "The elaborate cross-talk between macrophages, MDSCs, and tumor cells result in differential production of IL-6, IL-10, TNF-α, and NO, suggesting that the interaction between these cells has the potential to significantly alter the inflammatory milieu within the tumor microenvironment." (PMID 26052505, 2015). "During the past few years, these activated tumor-associated fibroblasts have also been involved in the modulation of the antitumor immune response, especially by the secretion of soluble immunosuppressive factors in the tumor microenvironment (TGF-β, IL-1β, IL-6, and IL-10)." (PMID 26441986, 2015). "Leptin however upregulates pro-inflammatory and pro-tumor IL-6 yet does not alter anti-inflammatory IL-10 expression." (PMID 25599228, 2015). "The allelic model showed no close relationships of IL10 -592A > C SNP with tumor biological and clinical prognostic factors." (PMID 26112140, 2015). "In supernatants of HPV-positive tumors upon PMA and ionomycin stimulation we detected higher levels of IL-10, IL-17, IL-21, TNFα and IFNγ compared to supernatants of HPV-negative tumor samples; however, only the levels of IL-17 showed statistically significant differences (p = 0.030)." (PMID 25949860, 2015). "In tumor-bearing animals tumor growth has not stimulated the release of IL-10, and this cytokine profile was not modified by the treatment with indomethacin." (PMID 26347589, 2015). "Additionally, other cytokines (TGF-β, IL-10, CCL18, etc.)which can be released from TAMs also have the ability to promote tumor progression through the PI3K/Akt pathway." (PMID 26359357, 2015). "NF-κB may promote the tumor formation and progression through up-regulation of its downstream effectors including TGF-β, IL-10, CCL2, COX-2, VEGF and CCL22." (PMID 26683520, 2015). "Anti-inflammatory cytokines, such as IL-10 and TGF-β, contribute to tumor immune evasion." (PMID 26528286, 2015). "In addition, the tumor microenvironment, which includes IL-4, IL-13, TGF-β, and IL-10 further support the adoption of an M2 phenotype." (PMID 26198107, 2015). "For example, pDCs exposed to the tumor microenvironment of malignant human ovarian epithelial tumor cells induced IL-10-producing Tregs rather than T cell activation, thus promoting tolerance instead of anti-tumor immunity." (PMID 28536413, 2015).
tumor (continued). "The percentages of IL-10+CD14+CD169+ circulating monocytes and TIMs in total CD14+CD169+ cells from CRC patients were significantly higher than that from the non-tumor subjects (3.79% vs. 0.76%, P<0.0001 for circulating monocytes; 7.12% vs. 1.23%, P<0.0001 for TIMs." (PMID 26509874, 2015). "HO-1 in the tumor niche promoted lung metastases by controlling VEGF and IL-10 production." (PMID 26418896, 2015). "However, these direct anti-tumor effects can be attributed not only to cytotoxicity but also to their cytokine-producing capacities (IFN-γ, TNF-α, IL-10)." (PMID 25674087, 2015). "In tumor microenvironments, MSCs can be activated by pro-inflammatory cytokines IFN-γ, TNF-α, or IL-1β, which are secreted by tumor cells and macrophages and then produce immunomodulatory molecules, such as IDO, PGE2, IL-6, IL-10, HLA-G5, and nitric oxide (NO)." (PMID 26694366, 2015). "This is puzzling because IL-4 and IL-10 are known to play immunosuppressive roles and yet are being produced alongside proinflammatory cytokines in the presence of premalignant (but not tumor) supernatant." (PMID 24698959, 2014). "Moreover, depletion of IL-10- and TGF-β-secreting γδ T cells by using a specific antibody enhanced the anti-tumor immunity and reduced tumor growth in xenografted mice." (PMID 25538706, 2014). "The increase of several immune cell-derived factors, such as interleukin-1 (IL-1), IL-6, IL-8, IL-10, and tumor necrosis factor alpha (TNF-α), has been described in tumor microenvironment: they sustain inflammatory process, contribute to tumor progression, and also exert proangiogenic activity." (PMID 24949467, 2014). "Over a 24 h time period, the IL-10 levels in the no tumor/trained group were analogous to IL-10 levels in the no tumor/non-trained control group and significantly lower than IL-10 levels in the tumor/non-trained group (P=0.0254)." (PMID 24520305, 2014). "In addition, the levels of TNF-α and IFN-γ were significantly increased, whereas the levels of IL-10 and TGF-β were significantly decreased in tumor-bearing mice treated with APS." (PMID 25251192, 2014). "IL-10 is a pleiotropic cytokine, which may favour NK cell-dependent lysis through MHC class-I down-regulation on tumor cells." (PMID 25512030, 2014). "M2-like macrophages stimulated with LPS + IFN-γ showed less anti-tumor activity than LPS + IFN-γ–stimulated M1-like macrophages, while IL-10–polarized M2-like macrophages were not able to inhibit tumor cell growth." (PMID 24612598, 2014). "Finally, γδreg produce IL-10 and TGF-β, which act on several cellular targets to promote immunosuppression at the tumor site and favor tumor progression." (PMID 25505472, 2014). "It is thus possible to hypothesize that other members of the Hsp70 family, when released from infected or tumor cells in vesicles, can engage a TLR2 pathway, leading to IL-10 production in myeloid cells, and polarizing macrophages to an M2 phenotype." (PMID 25419575, 2014). "First, the tumor environment can disrupt dendritic cell (DC) function of antigen-presenting cells to limit the generation of tumor reactive T cells, via transforming growth factor (TGF-β), interleukin (IL)-10, macrophage colony-stimulating factor (M-CSF), IL-6, hypoxia, and lactic acid." (PMID 24734218, 2014). "As results of tumor cell inoculation, marked decreases of spleen and submandibular lymph node weights, serum IFN-γ, splenic TNF-α, IL-1β and IL-10 contents, splenocytes and peritoneal NK cell activities were observed with histopathological atrophic changes of spleen and submandibular lymph nodes." (PMID 25477992, 2014). "Upon activation, human peripheral Vγ9Vδ2 T cells also can express IL-4, IL-10, and TGF-β and inhibit T cell proliferation, thus developing a regulatory profile that may play a role in the suppression of anti-tumor responses." (PMID 25538706, 2014).
tumor (continued). "The higher proliferation of M-406 cells observed when cultured with CMO from both Naïve CBi/L and CBi mice indicates that these media would contain factor/s like IL-2, IL-4, INF-γ, IL-10, TNF-α and many others, yet to be identified, capable to stimulate or inhibit tumor growth." (PMID 24885995, 2014). "Moreover, the production of several cytokines, such as IL-1, IL-6, IL-10, VEGF, and TGF-β by M2 TAMs elicits the proliferation and metastasis of tumor cells." (PMID 25505783, 2014). "Lack of IL-10 allows induction of pro-inflammatory cytokines and hinders anti-tumor immunity, thereby favoring tumor growth." (PMID 25056661, 2014). "Both of ILT4 and IL-10 expressions have no relation with other clinicopathological factors (age, histologic types, grade, tumor size, stages, or receptor status)." (PMID 24762057, 2014). "On the contrary, gemcitabine administered mice showed significant (P < 0.05) decreases of the splenic TNF-α and IL-1β, and nonsignificant but dramatic decreases of splenic IL-10 contents as compared with tumor-bearing control mice, respectively." (PMID 25477992, 2014). "The predominant expression of cytokines with immunosuppressive properties such as IL-10 and TGF-β1 could downregulate the cellular immune response favoring tumor implantation and promoting tumor growth in mice." (PMID 24808638, 2014). "The expressions of immunosuppressive proteins were found reduced in comparison with control mice, indicating that immunosuppressive cells in the tumor microenvironment also were suppressed, since TGF-β, IL-10 and IDO were related to the induction of Tregs and MDSCs." (PMID 25333973, 2014). "IL-10 is a potent tumour angiogenesis inhibitor released by AMs with or without LPS stimulation in vitro." (PMID 26316944, 2014). "In the presence of the tumor, implementing physical activity attenuated the expression of IL-10 (P=0.0469 tumor/trained vs. tumor/non-trained) towards control group levels (P>0.05, tumor/trained vs. no tumor/non-trained)." (PMID 24520305, 2014). "Important populations in all these pro-tumor processes are M2 macrophages, N2 neutrophils, regulatory T cells, and myeloid derived suppressor cells; the main effectors molecules are CSF-1, IL-6, metalloproteases, VEGF, PGE-2, TGF-β, and IL-10." (PMID 23577028, 2013). "On the other hand, studies in mouse tumor models have demonstrated that γδ T cells within the tumor microenvironment exert an inhibitory action on CTL and NK cytolytic activity through production of IL-10 and TGF-β, resulting in the induction of tumor-specific immune tolerance." (PMID 23616948, 2013). "Although the molecular mechanisms and roles underlying the effects of IL-10 have not been well characterized, the biological activities of IL-10 in tumor immunity and pathology appear highly context-dependent." (PMID 23533029, 2013). "Twist and miR-34a may regulate the effect of tumor cells inducing myeloid-derived suppressor cells via TGF-β and/or IL-10." (PMID 24129179, 2013). "Microglial cells appear to promote tumour growth directly (e.g. by producing growth factors) as well as indirectly by the secretion of immunosuppressive cytokines (e.g. TGF-β, IL-10) and the expression of molecules inducing apoptosis in lymphocytes (e.g. Fas ligand)." (PMID 23132370, 2013). "Tumor cells secreted many immune suppressing cytokines such as TGF-β, VEGF, IL-10 and PGE2." (PMID 24129179, 2013). "Alternatively, a body of both clinical and pre-clinical data is emerging showing that IL-10 can influence tumor growth and progression by non-immune-related phenomena such as the inhibition of angiogenesis and induction of tumor cell apoptosis." (PMID 23533029, 2013). "We show that upon co-culturing APC with various primary and tumor cell lines STAT3 phosphorylation and IL-10 expression are induced, and such regulation could be suppressed by specific CD47 siRNAs and shRNAs." (PMID 24073274, 2013).